EGFR (epidermal growth factor receptor)
Diseases named in the same sentence as EGFR in open-access papers (continued):
Sharing a sentence is not in itself a finding about the gene and the disease.
viral infection (continued). "Thus, EGFR gene expression is mandatory for viral infection, but cannot be considered a biomarker of reovirus selectivity." (PMID 39772250, 2024). "Molecular interactions between NTCP and EGFR are important for supporting viral infection." (PMID 38136637, 2023). "The ligand of these receptors is betacellulin (BTC), and a previous study indicated that it might be useful in preventing an excessive fibrotic response to viral infections (such as SARS-CoV) by inhibiting EGFR signaling." (PMID 37936693, 2023). "Pretreatment of IAV with fucoidan KW may interferes with the activation of EGFR pathway to resist virus infection." (PMID 37544014, 2023). "miR-146a-5p has also been implicated in a number of biological processes including regulation of the development of viral infections and cancer tumour suppression, for example in the inhibition of both EGFR and NF-kB signalling and reduction of the metastatic potential of cancers." (PMID 37319303, 2023). "Understanding EGFR significance in both normal cellular processes and viral infections may not only help develop innovative antiviral therapies but also provide a deeper understanding of the intricate roles of EGFR signaling in infectious diseases." (PMID 38136637, 2023). "However, upon viral infection, activated EGFR induces the stimulation of highly activated N-WASP to promote cell movement, while N-WASP knockdown inhibits HCMV-induced monocyte motility." (PMID 38136637, 2023). "Activated EGFR recruits several major downstream signaling pathways during viral infection." (PMID 35847084, 2022). "Moreover, the consistent result of reduced viral infection was also acquired in hBMECs with the use of EGFR-specific inhibitors AG1478 or gefitinib." (PMID 35847084, 2022). "Another important question is whether stress-activated EGFR is a signaling nexus integrating multiple innate immune responses to viral infections." (PMID 35083168, 2021). "For example, EGFR signaling limits antiviral activity associated with DDX60 (DExD/H-Box Helicase 60), an RNA helicase that recognizes short viral dsRNA in the cytosol during a viral infection." (PMID 35083168, 2021). "It has been documented that TLRs could activate ADAM17 leading to tumor necrosis factor alpha (TNF-α), interleukin-6 (IL-6) and epidermal growth factor receptor (EGFR) after viral infection." (PMID 33926110, 2021). "However, given that these same pathways are fundamentally important for normal physiology, their inhibition will also impair key EGFR functions particularly those involved in repairing cell damage resulting from severe viral infections." (PMID 35083168, 2021). "Excessive intracellular ROS in response to viral infection could regulate many cellular signalings including cell cycle through modulating the phosphorylation status of growth factor receptors such as EGFR." (PMID 32877289, 2020). "Discovering the tumor-derived exosomes in cancerous mice revealed the releasing of epidermal growth factor receptor (EGFR) in host macrophages which cause a decrease in interferon-1 gene expression, and thereby the immune response is reduced against viral infection." (PMID 32509768, 2020). "As our previous results demonstrated that BoHV-1 productive infection led to activation of EGFR in both A549 and MDBK cells, we next investigated whether EGFR signaling played an important role in virus infection." (PMID 32846937, 2020). "We then investigated the effects of EGFR on virus infection in MDBK cells." (PMID 32846937, 2020). "Although these stress-induced EGFR responses are thought to provide cancer cells with a survival advantage and resistance to therapeutics, their potential roles during viral infections are largely unknown." (PMID 31425554, 2019). "Moreover, EGFR signaling plays an essential role in this process at the early stages of virus infection, indicating that viral endocytosis is required for the induction of endosomal tubulation." (PMID 31192164, 2019).
viral infection (continued). "In addition to viral infection, EGFR has been documented to play a role in increasing IL-6 expression." (PMID 31470515, 2019). "Thus there is a unique role for SOCS5 in regulating viral activation of the EGFR in lung epithelial cells and this study confirms an important role for endogenous EGFR activity in facilitating viral infections." (PMID 28195529, 2017). "We next sought to test the hypothesis that SOCS5 might be regulating viral infection via negative regulation of EGFR and/or PI3K signaling." (PMID 28195529, 2017). "Our work identifying opposing viral regulators of EGFR offers a powerful path towards defining the mechanistic underpinnings and the significance of viral-mediated control of EGFR and its downstream signaling pathways to viral infection." (PMID 27218650, 2016). "EGFR signaling may be modulated during viral infection in a number of ways, including phosphorylation, ubiquitination, and trafficking." (PMID 27218650, 2016). "In influenza-infected mice, pretreatment with EGFR inhibitor results in decreased viral infection, decreased macrophage inflammatory protein (MIP)-2, a murine IL-8 homolog, secretion, and decreased neutrophil recruitment but increased IP-10 and IFN-λ secretion in influenza-infected mice." (PMID 26033355, 2015). "However, the screens that we have performed here do not take into account the dependence of innate immune responses to viral infection, in both tumor cells and host immune effectors, upon cell signaling pathways, such as EGFR/Ras, in the tumour cells." (PMID 22920673, 2012). "Similarly, vaccinia virus infection of HeLa cells is EGFR dependent, yet the virus also infects CHO cells using an undefined alternate mechanism." (PMID 22346752, 2012). "While EGFR mutations drive tumorigenesis through constitutive activation of downstream signaling pathways (e.g., PI3K/AKT, RAS/RAF/MEK), viral infections may modulate these same pathways, potentially enhancing tumor aggressiveness or altering therapeutic response." (PMID 41327362, 2025). "We speculate that this pathway has a yet unclear benefit for the efficiency of viral infections, because both the KD of EGFR and the pharmacological inhibition and translocation of EGFR from the plasma membrane, by using the MEK1/2 inhibitor U0126, reduced the infectivity SARS-CoV-2." (PMID 37402592, 2023). "Thus, the EGFR/ERK signaling pathway hijacked by viruses might be a common immune escape strategy for viral infection." (PMID 35847084, 2022). "For example, overexpression of IFI6-16 inhibited genome replication and gene expression of HBV (hepatitis B virus) in HepG2 cells, and researchers also found that IFI6-16 could inhibit HCV (hepatitis C virus) infection by impairing EGFR mediated CD81 co-localization with claudin-1." (PMID 35632802, 2022). "Kaempferol might regulate inflammation, oxidative stress, immunity, virus infection, cell growth process and metabolism through targeting EGFR, IL-17, TNF, HIF-1, PI3K/AKT and Toll-like receptor signaling pathways to perform anti-COVID-19/PF co-occurrence effect." (PMID 35754492, 2022). "Interestingly, EGFR, the epidermal growth factor receptor, is not only a key membrane receptor involved in cell survival and tissue remodelling, but it can also mediate the macrophage activation during bacterial and virus infection." (PMID 33226440, 2021). "In addition to providing a mechanism for increasing basal NF-κB signaling, the stress-induced EGFR pathway may amplify inflammatory responses induced by stimuli that activate a canonical NF-κB activation pathway during viral infections." (PMID 35083168, 2021). "Interestingly, both phospholipase C-γ1 (PLC-γ1) and Akt, canonical downstream effectors of EGFR, were activated following virus infection in A549 cells, while Gefitinib could inhibit the activation of PLC-γ1 but not Akt." (PMID 32846937, 2020).
viral infection (continued). "Finally, we have shown in vivo and in primary human cells, that SOCS5 acts to negatively regulate EGFR and PI3K signaling and while both are important positive mediators of influenza virus infection, it is SOCS5 restriction of EGFR activity, which limits viral infection in lung epithelium." (PMID 28195529, 2017). "Although the key role of EGFR in HCMV entry into epithelial cells is still questionable, EGFR activation, alongside integrin αvβ3, appears to be essential for viral infection in epithelial cells." (PMID 40002177, 2025). "FMDV RNA copy numbers were significantly reduced in cells treated with 30 μM Lapatinib, indicating that inhibiting EGFR/ERBB2 tyrosine kinase activity and activation of this pathway can inhibit virus infection." (PMID 38512977, 2024). "However, whether viral infections induce EGFR core fucosylation remains unclear." (PMID 38253527, 2024). "Many viral infections (e.g., HCV, VSV, and HSV-1) stimulate the EGFR/AKT endocytosis signaling pathways." (PMID 38253527, 2024). "However, the role of EGFR glycosylation and core fucosylation in viral infections remains unclear." (PMID 38253527, 2024). "In the event of viral infection, phosphorylation of DDX60 can be induced by epidermal growth factor receptor (EGFR), reducing antiviral activity." (PMID 38115996, 2023). "Multiple stimuli induce expression of IEGs that include trophic factors downstream of receptor tyrosine kinases (RTKs, e.g., EGFR, TrkA, TrkB), calcium channels (e.g., NMDAR), neurotransmitters (glutamine, dopamine), and viral infection." (PMID 37234916, 2023). "SARS-CoV-2 activates the conserved EGFR-RAS-MAPK pathway through a novel mechanism that involves an ACE2-EGFR cross talk and pharmacological inhibition of the MAPK pathway is able to reduce viral infection." (PMID 37402592, 2023). "Taken together, our results demonstrate the activation of the RAS–MAPK pathway in response to spike protein binding, that EGFR is a novel cofactor of ACE2 that promotes SARS-CoV-2 entry and that inhibition has potential to reduce viral infection." (PMID 37402592, 2023). "Yet, the key integrin receptors, α1β1 and αVβ3, together with EGFR had moderate or strong expression in SCT, which provides the molecular basis for viral infection." (PMID 36561369, 2022). "Here, we reported that BoHV-1 infection activates EGFR signaling in two cell types (MDBK and A549 cells), which in turn play an important role in the virus infection." (PMID 32846937, 2020). "Overall, these results indicate that BoHV-1 infection leads to the activation of EGFR in both A549 and MDBK cells, which in turn plays an important role in virus infection." (PMID 32846937, 2020). "Based on our observation that UL135, an activator of replication, induced the turnover of EGFR and EGFR is transcriptionally downregulated during replication in fibroblasts, we hypothesized that reduced EGFR levels and activity in the context of viral infection promoted virus replication." (PMID 27218650, 2016). "Significantly enriched pathways included JAK-STAT signaling, chemokine signaling, EGFR-TKI resistance, PI3K complex signaling, and viral infection pathways, particularly those related to Kaposi sarcoma virus and HSV-1, indicating immunoregulatory and antiviral roles." (PMID 42075882, 2026). "After infection with PRRSV, we observed that viral infection was decreased in EGFR-knockdown PAMs compared to those treated with a non-targeting siRNA (si-NC)." (PMID 39469460, 2024). "For example, CPV can trigger host G1/S cell cycle arrest via the EGFR (Y1086)/p27 and EGFR (Y1068)/STAT3/cyclin D1 axis, and in the late stage of viral infection, nuclear assembly of the progeny capsids is accompanied by virus-induced cell cycle triggering host cell G2/M phase arrest." (PMID 38384266, 2024). "Many viral infections (e.g., HCV, VSV) stimulate the EGFR/AKT endocytosis signaling pathways." (PMID 38253527, 2024).
viral infection (continued). "The multifaceted role of the epidermal growth factor receptor (EGFR) is of paramount importance not only in understanding human diseases in relation to cell survival, proliferation, and cellular homeostasis but also in the intricate realm of viral infections." (PMID 38136637, 2023). "Moreover, another recent research has found that PEDV S protein directly interacts with epidermal growth factor receptor (EGFR) and activates EGFR downstream signal transduction, inhibiting IFN and exacerbating viral infection." (PMID 35237253, 2022). "The inconsistent result of EGFR in different virus infections is not surprising, which also appeared in the previous study." (PMID 35847084, 2022). "Furthermore, myricetin also down-regulates the host EGFR/PI3K/Akt (epidermal growth factor receptor/phosphoinositide 3-kinase/Akt or protein kinase B) signaling pathway, which inhibits viral infection and replication." (PMID 34834309, 2021). "EGFR is also involved in innate immunity pathways regulated by TLR3, which is localized to endosomes where it recognizes double-stranded RNA (dsRNA) replication intemediates produced during viral infections." (PMID 35083168, 2021). "Akt, a canonical downstream effector of the EGFR pathway, is important for BoHV-1 infection in MDBK cells, but its role during virus infection in A549 cells has been unknown." (PMID 32846937, 2020). "Although both receptor proteins were phosphorylated at Ser1046/1047 shortly after viral infection, EGFR underwent stress-induced autophosphorylation in cells expressing WT but not kinase dead-EGFR." (PMID 31425554, 2019). "More recently, EGFR signalling has been shown to improve the efficiency of infection of CD34+ cells as well, with EGFR-blocking antibodies and inhibitors of EGFR/PI3K signalling leading to less internalisation of virus particles if applied prior to viral infection." (PMID 29547547, 2018). "Inhibitors of the EGFR pathway and the effectors Pak1, Rac1 and PKC reduced viral infection." (PMID 28596575, 2017). "Recently, we and others have shown that viral infection and the stimulation of TLR3 induces the expression and production of MUC5AC in airway epithelial cells mainly via epidermal growth factor receptor (EGFR) and extracellular signal-regulated kinase (ERK) signaling pathways." (PMID 27677339, 2016). "While EGFR and Nectin2 were not enriched, Neo1 was enriched 2.78-fold upon virus infection." (PMID 40623098, 2025). "A recently published study reported that EGFR and its major downstream signaling pathway, the mitogen-activated signaling pathway (MAPK), are activated during SARS-CoV-2 infection, indicating that viral infection is closely related to EGFR signaling and its downstream pathways." (PMID 39291996, 2024). "Therefore, the identified cross talk between EGFR and ACE2 could not only pave the route for new strategies to fight viral infections but should also be considered in future cancer and RAAS studies." (PMID 37402592, 2023). "Moreover, and not coincidentally, activated EGFR has also been identified to be involved in the production of interferon signaling molecules in other cases, such as cancer and viral infections." (PMID 35847084, 2022). "Even though the process of viral infection in attachment and entry was not noticeably influenced, the induction of IFNs in EGFR-KO hBMECs was significantly increased, which may account for the decreased viral production." (PMID 35847084, 2022). "While EGFR inhibition by gefitinib did not impact STAT1, it was interestingly able to rescue the otherwise decreased levels of STAT2 phosphorylation caused by vanadate/virus infection." (PMID 35572196, 2022).
viral infection (continued). "However, EGFR expression in our 240 paired HCC tumor (T) tissue specimens was markedly higher relative to normal (N), and it was increased at the advanced pathological stage, larger tumors, and virus infection." (PMID 35999564, 2022). "In addition, the effect of viral infection on formation of productive interactions between internalized receptors and PTP1B regulating EGFR dephosphorylation at endosome-ER membrane contacts sites remains unknown." (PMID 35083168, 2021). "Furthermore, EGFR plasma concentrations were significantly higher in HCC patients in the presence of HCV and HBV infection, suggesting that plasma EGFR could serve as a marker for HCC, in particular when carcinogenesis is affected by virus infection." (PMID 26729094, 2015). "Consequently, EGFR may not represent a bona fide entry receptor whose presence is absolutely required for cell entry, but engagement could play an important role in tuning the cellular environment towards one more conducive to successful viral infection." (PMID 29547547, 2018). "As surface expression of EGFR is not well established in CD34+ HPCs, we first investigated EGFR surface levels in the context of WT, UL135STOP and UL138STOP virus infection using EGF-647." (PMID 27218650, 2016). "Rather than inhibiting viral infection, EGF actually promotes the internalization of HBV, most likely due to the fact that EGFR may function as a co-receptor for HBV entry." (PMID 39746094, 2025). "Interestingly, we found that both EGFR and PI3K, but not PLA2, were driving the induction of LDs following viral infection, however this was not the case for LDs induced by IFNs." (PMID 34262037, 2021).